DIDO1 (death inducer-obliterator 1)
Description:
Putative transcription factor, weakly pro-apoptotic when overexpressed (By similarity). Tumor suppressor. Required for early embryonic stem cell development. [Isoform 2]: Displaces isoform 4 at the onset of differentiation, required for repression of stemness genes.
Synonyms: DIO-1; DATF-1; C20orf158; DATF1; KIAA0333; DIO1; dJ885L7.8; FLJ11265; BYE1; DIDO2; DIDO3
Tractability: PROTAC: UniProt records ubiquitination sites on it; ubiquitination databases record sites on it; its protein half-life has been measured.
Gene: Protein-coding gene on chromosome 20 (62,877,738 to 62,937,952, reverse strand). Ensembl gene ENSG00000101191.
Subcellular location: Cytoplasm; Nucleus; Cytoplasm, cytoskeleton, spindle
Subcellular location (Human Protein Atlas): Nucleoplasm; Cytosol; Vesicles
Pathways (Reactome):
Reproduction: Meiotic synapsis
Gene Ontology:
Molecular function: protein binding; RNA binding
Biological process: apoptotic signaling pathway; DNA-templated transcription
Cellular component: cytoplasm; nucleus; spindle
Genetic constraint (gnomAD): Loss-of-function variants: 16 observed, 103.25 expected, observed/expected ratio (o/e) 0.15, 90% interval 0.1 to 0.23. The upper end of that interval is the gene's LOEUF score, 0.23, which puts it in group 1 of 6, group 1 being the genes least tolerant of losing a copy. Missense variants: 2,958 observed, 3,040 expected, observed/expected ratio (o/e) 0.97, 90% interval 0.94 to 1. Synonymous variants: 1,344 observed, 1,247.1 expected, observed/expected ratio (o/e) 1.08, 90% interval 1.03 to 1.13.
Homologues: Orthologues: chimpanzee DIDO1 (99% identical), macaque DIDO1 (97% identical), rat Dido1 (75% identical), mouse Dido1 (75% identical), guinea pig DIDO1 (74% identical), dog DIDO1 (74% identical), tropical clawed frog dido1 (48% identical), zebrafish si:ch73-181d5.4 (22% identical). Paralogues in human: PHF3 (19% identical), SPOCD1 (9% identical).
Diseases named in the same sentence as DIDO1 in open-access papers:
DIDO1 is named in the same sentence as 44 diseases in open-access papers, as found by Europe PMC text mining. Sharing a sentence is not in itself a finding about the gene and the disease. The quoted sentences say what the papers report.
melanoma (5 papers, 2013 to 2024). A malignant, usually aggressive tumor composed of atypical, neoplastic melanocytes. "For example, DIDO1 promotes the progression of melanoma and inhibits the apoptosis of melanoma cells." (PMID 39514105, 2024). "BMP-induced DIDO1 promotes cell attachment, migration, invasion, and apoptosis resistance in melanoma." (PMID 34103026, 2021). "It should be noted that DIDO1 is the target gene of BMP and promotes cell attachment, migration, invasion, and apoptosis resistance in melanoma." (PMID 34103026, 2021). "The DIDO1, which has recently been reported to promote BMP-induced progression and apoptosis resistance in melanoma cells." (PMID 24098708, 2013).
Obesity (4 papers, 2021 to 2025). Accumulation of substantial excess body fat. "By contrast, the prevalence of obesity among female carriers of PTV variants in DIDO1 and SLC12A5 was more than 80%, albeit there were relatively fewer carriers (12 of 14 and 9 of 11 carriers were obese, respectively) (PHeterogeneity = 9.9 × 10−6 and PHeterogeneity = 2.6 × 10−4, respectively)." (PMID 37601970, 2023). "DIDO1 is only upregulated in the NASH dataset, and lastly, CDA is downregulated in obesity and NASH and upregulated in the other two datasets." (PMID 34833079, 2021). "Additionally, we investigated five genes, PRDM2, CXCL1, PHLDA1, DIDO1, CDA, which were commonly expressed in all datasets including depression, obesity, diabetes, and NASH." (PMID 34833079, 2021).
atherosclerosis (2 papers, 2021 to 2024). A disease characterized by the build-up of fatty material and calcium deposition in the arterial wall resulting in partial or complete occlusion of the arterial lumen. "For instance, the antigenic proteins of other atherosclerosis autoantibody markers, DIDO1-Abs, CPSF2-Abs, and FOXJ2-Abs, were highly expressed in the carotid atherosclerotic plaques." (PMID 38732153, 2024). "Serum antibody levels of DIDO1, FOXJ2, and CPSF2 are useful in predicting the onset of atherosclerosis-related AIS caused by kidney failure, hypertension, and DM, respectively." (PMID 34103026, 2021).
diabetes (2 papers, 2021). "Compared with HDs, a significant increase in antibody levels of the DIDO1 protein and peptide in patients with AIS, transient ischemic attack (TIA), and chronic kidney disease (CKD) but not in those with acute myocardial infarction and diabetes mellitus (DM)." (PMID 34103026, 2021).
gastric cancer (2 papers, 2021 to 2025). A primary or metastatic malignant neoplasm involving the stomach. "Moreover, a newly identified circular RNA, death-inducer obliterator 1 (circDIDO1), encodes 529 aa protein (DIDO1-529aa) and is expressed at low levels in gastric cancer." (PMID 40227215, 2025).
bladder cancer (1 paper, 2023). "Lastly, the death-inducer obliterator or DIDO1 is a putative transcription factor with known apoptotic functions, highly expressed in several diseases including bladder cancer and oesophageal squamous cell carcinoma." (PMID 37060086, 2023).
breast carcinoma (1 paper, 2017). "Among 11 most commonly amplified/overexpressed PHF genes, we found that three genes, ZMYND8, PHF20, and DIDO1, were significantly highly expressed in advanced-stage breast cancers (T-test: Stage I+II vs III+IV; p < 0.05)." (PMID 28055972, 2017). "We found that ZMYND8 and PHF20, but not DIDO1, also had significantly higher expression in advanced stages of Luminal breast cancers (p < 0.05)." (PMID 28055972, 2017).
cerebral infarction (1 paper, 2021). An ischemic condition of the brain, producing a persistent focal neurological deficit in the area of distribution of the cerebral arteries. "Likewise, the antibody levels of the DIDO1, FOXJ2, and CPSF2 peptides were positively correlated with a risk of cerebral infarction: odds ratios (95% CIs) of the highest quartile were 2.66 (1.43–4.95), 2.24 (1.27–3.95), and 2.41 (1.33–4.37), respectively." (PMID 34103026, 2021).
chronic myelocytic leukemia (1 paper, 2025). "Other studies have indicated that BCR-ABL1 translocation (Philadelphia chromosome,Ph) in chronic myelocytic leukemia (CML) may modulate DIDO1 expression in a JAK2V617F-independent manner." (PMID 40287726, 2025).
collagen disease (1 paper, 2021). "It is possible that DIDO1-Ab and FOXJ2-Ab are discriminant in the case of AIS of which one of the causes is a collagen disease." (PMID 34103026, 2021).
esophageal squamous cell carcinoma (1 paper, 2025). Esophageal squamous cell carcinoma (ESCC) is a type of esophageal carcinoma (EC) that can affect any part of the esophagus, but is usually located in the upper or middle third. "It has been reported that DIDO1 can be suggested as a marker for the primary esophageal squamous cell carcinomas." (PMID 40666499, 2025).
glioblastoma (1 paper, 2014). The most malignant astrocytic tumor (WHO grade IV). "Importantly, Bye1 has two human homologues possessing the same domain organization: PHF3 and the Dido gene encoding three proteins Dido1, 2 and 3, described as putative transcription factors and abnormally expressed in glioblastoma and myeloproliferative disorders." (PMID 25029256, 2014).
Hypertension (1 paper, 2021). The presence of chronic increased pressure in the systemic arterial system. "Although the present study suggests kidney failure-associated DIDO1-Ab, hypertension-related FOXJ2-Ab, and DM-related CPSF2-Ab markers as risk factors of AIS, further study using the increasing number of specimens is needed to verify the suggestion." (PMID 34103026, 2021). "Receiver operating characteristic curves showed that serum DIDO1 antibody levels were highly associated with CKD, and correlation analysis revealed that serum anti-FOXJ2 antibody levels were associated with hypertension." (PMID 34103026, 2021). "Serum DIDO1-Ab, FOXJ2-Ab, and CPSF2-Ab appear to be useful for diagnosing AIS and may originate from kidney disease, hypertension, and DM, respectively." (PMID 34103026, 2021).
liver fibrosis (1 paper, 2024). "Previous studies have indicated that EV circ-death inducer-obliterator 1 (circ-DIDO1) is positively correlated with liver fibrosis because of its ability to suppress HSC activation via the miR-141-3p/PTEN/AKT pathway." (PMID 39396032, 2024).
lung adenocarcinoma (1 paper, 2023). A carcinoma that arises from the lung and is characterized by the presence of malignant glandular epithelial cells. "Zhang and collaborators (2021) have identified seven N6-methyladenosine-related immune prognostic genes (i.e., PSMD10P1, DIDO1, ABCA5, CIITA, PRC1, ZWILCH, and ANLN) for lung adenocarcinoma (LUAD)." (PMID 37189849, 2023).
ovarian carcinoma (1 paper, 2007). A malignant neoplasm originating from the surface ovarian epithelium. "Among this set, however, three displayed reduced levels in the presence of AZT: breast and ovarian cancer susceptibility (BRCA1), human homolog of double minute 2 (HDM2), and death inducer-obliterator 1 (DATF1)." (PMID 17967062, 2007).
rheumatoid arthritis (1 paper, 2021). A chronic, systemic autoimmune disorder characterized by inflammation in the synovial membranes and articular surfaces. "Serum DIDO1-Ab and FOXJ2-Ab levels were significantly associated with rheumatoid arthritis and SLE but not with Sjögren’s syndrome or ulcerative colitis." (PMID 34103026, 2021). "Serum DIDO1-Ab and FOXJ2-Ab levels were significantly higher in patients with rheumatoid arthritis and SLE (but not in those with Sjögren’s syndrome or ulcerative colitis) than in HDs." (PMID 34103026, 2021).
cancer (11 papers, 2012 to 2025). A tumor composed of atypical neoplastic, often pleomorphic cells that invade other tissues. "DIDO1 has anti-apoptotic functions and is necessary for cell proliferation and survival in many types of cancer cells." (PMID 37601970, 2023). "Further studies are needed to clarify the fine-tuned regulation of DIDO1 gene expression in normal cells and its role in the development and progression of human cancers." (PMID 34384442, 2021). "In addition, we identified three heterozygous candidate missense variants in known cancer susceptibility genes (BMPR1A,BRIP1, and SRC), three truncating variants in possibly novel cancer genes (CLSPN,SEC24B, SSH2) and four candidate missense variants in ACACA, NR2C2, INPP4A, and DIDO1." (PMID 30809968, 2019). "Notably, serum DIDO1-Ab and CPSF2-Ab levels were not significantly different between HDs and patients with any type of cancer." (PMID 34103026, 2021).
tumor (7 papers, 2017 to 2025). "Although it is an intriguing hypothesis that the mutations in cell death pathways (CASP8, DIDO1) observed in head/neck cancer could be a tumor adaptation to ongoing immune activity, additional experiments will be necessary to establish this." (PMID 28749946, 2017). "DIDO1 can exert its tumor suppressor role through apoptosis induction and its oncogenic role via the activation of NANOG." (PMID 30157793, 2018). "Noteworthy, PRMT2 was recently reported to be induced and contribute to HCC tumorigenesis, DIDO1 has been involved in numerous types of tumors, and PRDM2 is a tumor suppressor epigenetically repressed in HCC." (PMID 37620598, 2023). "In addition, a recent study demonstrated that a novel circular RNA DIDO1 could specifically bind to PRDX2 and promote its ubiquitination and degradation in a RBX1-dependent way, which inhibited its downstream signaling pathways to suppress tumor progression." (PMID 35813474, 2022).
infection (2 papers, 2008 to 2021). The state of being infected such as from the introduction of a foreign agent such as serum, vaccine, antigenic substance or organism. "DOCK11, DIDO1 and DMXL2 were only found in leukocytes during infection with the EuA lineage: these are associated with innate immunity and inflammation activation." (PMID 34141493, 2021). "Transcripts of caspase 3 (CASP3), Acyl coenzyme A-binding protein (DBI), death inducer-obliterator-1 (DIDO1) and Bcl2-related protein A1 (BCL2A1), are pro-apoptotic proteins or induced by apoptosis, and were down-modulated upon infection." (PMID 18495030, 2008).
head/neck tumors (1 paper, 2017). "Finally, two different cell death regulators, CASP8 and DIDO1, were often mutated in head/neck tumors that had higher lymphocyte infiltrates." (PMID 28749946, 2017).
DIDO1 also shares sentences with these, for which no sentence is quoted: acute myocardial infarction (1 paper); anemia (1); Ataxia (1); autoimmune disease (1); chronic kidney disease (1); CNS tumors (1); colorectal adenoma (1); colorectal cancer (1); colorectal tumors (1); depression (1); hematopoietic cancer (1); Hepatitis (1); ischemic stroke (1); kidney disease (1); kidney failure (1); leukemia (1); lymphopenia (1); myeloproliferative disorder (1); pulmonary diseases (1); Sjögren’s syndrome (1); transient ischemic attack (1); ulcerative colitis (1); viral infection (1).